GOLGA7B (golgin A7 family member B)
Description:
Play a role in cell adhesion by regulating the plasma membrane localization of the palmitoyltransferase ZDHHC5. May be involved in protein transport from Golgi to cell surface.
Synonyms: C10orf132; C10orf133; bA459F3.4; bA451M19.3
Tractability: Antibody: UniProt places it where antibodies can reach, with high confidence; its Gene Ontology location is reachable by antibodies, with medium confidence. PROTAC: its protein half-life has been measured.
Gene: Protein-coding gene on chromosome 10 (97,849,295 to 97,871,580, forward strand). Ensembl gene ENSG00000155265.
Subcellular location: Cell membrane; Golgi apparatus membrane
Gene Ontology:
Molecular function: enzyme binding; protein binding
Biological process: protein targeting to membrane
Cellular component: plasma membrane; palmitoyltransferase complex; Golgi membrane
Genetic constraint (gnomAD): Loss-of-function variants: 16 observed, 20.01 expected, observed/expected ratio (o/e) 0.8, 90% interval 0.54 to 1.21. The upper end of that interval is the gene's LOEUF score, 1.21, which puts it in group 5 of 6, group 1 being the genes least tolerant of losing a copy. Missense variants: 169 observed, 234.34 expected, observed/expected ratio (o/e) 0.72, 90% interval 0.63 to 0.82. Synonymous variants: 87 observed, 86.24 expected, observed/expected ratio (o/e) 1.01, 90% interval 0.85 to 1.21.
Homologues: Orthologues: chimpanzee GOLGA7B (100% identical), dog GOLGA7B (99% identical), mouse Golga7b (99% identical), pig GOLGA7B (99% identical), guinea pig GOLGA7B (97% identical), rabbit GOLGA7B (96% identical), rat Golga7b (91% identical), tropical clawed frog golga7b (88% identical), macaque GOLGA7B (83% identical), zebrafish golga7ba (74% identical), zebrafish golga7bb (69% identical), Drosophila melanogaster CG5447 (43% identical), and 1 more. Paralogues in human: GOLGA7 (62% identical).
Diseases named in the same sentence as GOLGA7B in open-access papers:
GOLGA7B is named in the same sentence as 6 diseases in open-access papers, as found by Europe PMC text mining. Sharing a sentence is not in itself a finding about the gene and the disease. The quoted sentences say what the papers report.
adenoma (1 paper, 2022). A neoplasm arising from the epithelium. "Six predicted Mir34a targets (Arhgap44, Ccnjl, Clec16a, Esyt3, Golga7b, Grap) were up-regulated in both Mir34a-deficient adenomas and tumoroids." (PMID 36147476, 2022).
prostate carcinoma (1 paper, 2018). A carcinoma that arises from epithelial cells of the prostate gland. "Five genes CGNL1, SUPV3L1, TATDN2, CASKIN1, and GOLGA7B are of unknown functions in either prostate cancer tumorigenesis or tumorigenesis in general." (PMID 30024105, 2018).
tumor (3 papers, 2017 to 2024). "In addition, the Human Protein Atlas database confirmed that the protein expression of GOLGA7B was significantly higher in CCA tumor tissues." (PMID 36591499, 2022). "GOLGA7B and GOLGA1 were identified as novel genes associated with the tumor grade of ESCC." (PMID 28904855, 2017). "Compared with normal tissues, both GOLGA7B and AGAP2−AS1 RNA were highly expressed in tumor tissues." (PMID 36591499, 2022). "GOLGA7B and AGAP2−AS1 were highly expressed in tumor tissues from the testing group, similar to the case in the training group." (PMID 36591499, 2022).
cancer (1 paper, 2022). A tumor composed of atypical neoplastic, often pleomorphic cells that invade other tissues. "GOLGA7B is a novel and promising target, and further study is required to illustrate the molecular mechanisms by which it inhibits cancer progression." (PMID 36591499, 2022). "GOLGA7B is a novel accessory protein that has rarely been studied in the context of carcinoma." (PMID 36591499, 2022). "Nevertheless, clarifying the molecular pathways by which GOLGA7B and AGAP2-AS1 regulate cancer development and alter prognosis will require more in vivo and in vitro research." (PMID 36591499, 2022).
GOLGA7B also shares sentences with these, for which no sentence is quoted: colorectal cancer (1 paper); lung carcinoma (1).